RAG2 (recombination activating 2)
Diseases named in the same sentence as RAG2 in open-access papers (continued):
Sharing a sentence is not in itself a finding about the gene and the disease.
tumor (continued). "We found that 5AZA-mediated tumor inhibition disappeared in Rag2 mice." (PMID 34976218, 2022). "However PD-1 expression on ILC2s greatly enhances tumor progression, as evidenced by the increase in tumors in Rag2-/- control mice depleted of NK cells." (PMID 34531874, 2021). "In order to directly test whether ILC2s had a direct effect on the inhibition of tumor progression, we injected B16 cells into a cohort of Rag2-/- γc-/- mice, a strain that lacks all B, T, and innate lymphoid cells." (PMID 34531874, 2021). "Finally, ETV6-RUNX1 positive tumours were associated with enrichment for TBLXR1 and RAG1/RAG2 deletions." (PMID 34753926, 2021). "To explore whether ILC2s in our context relied upon adaptive immunity for potential anti-tumor properties and cytokine production, we utilized Rag2-/- PD-1-/- and control Rag2-/- mice." (PMID 34531874, 2021). "Additionally, tumor metastasis drastically decreased in Rag2-/- PD-1-/- mice as compared to the Rag2-/- control." (PMID 34531874, 2021). "We compared tumor growth between wild type and immune-compromised mice (Rag2-/-)." (PMID 32122466, 2020). "Our adoptive cell transfer experiments sought to confirm that G-CSFR−/− CD4+ cells, which were prevalent in anti-tumor phenotypes, could transfer those properties to the tumor microenvironment of Rag2−/− mice, which lack T cells." (PMID 33042110, 2020). "In addition, we successfully used our workflow on sorted tumor cells from Tg(rag2:mMyc;rag2:GFP) or Tg(dβh:MYCN, dβh:GFP) adult zebrafish (data not shown)." (PMID 30894119, 2019). "Normal mammary gland was compared to those from tumour-bearing mice (Rag2 and CD1 nude)." (PMID 29100335, 2017). "To improve efficiency we implanted tumour fragments into the immunocompromised Rag2-/-γC-/- mouse." (PMID 29145505, 2017). "After the intravitreal implantation of Y79 cells in Rag2 KO mice, tumours formed in the eye and gradually spread, and later could also be found in the brain." (PMID 27694105, 2016). "Thus to examine T cell infiltration in tumors grown in the absence of T cells, we transferred 3×106 CD3+ T cells into a cohort of PANC02 tumor-bearing RAG2−/− mice, 3 days before harvesting their 3-week-old PANC02 tumors." (PMID 27177227, 2016). "The number of circulating tumor cells detected in murine blood by using qRT-PCR varied between 0 and 124 cells per ml (mean 24 cells per ml) in the rag2 mice compared to the pfp/rag2 mice where numbers varied between 1 and 368 cells per ml (mean 68 cells per ml)." (PMID 25373310, 2014). "The proliferation index in TSGs maintained in RAG2−/−γc−/− mice was 97% of the parent tumor." (PMID 23985008, 2013). "To further provide evidence for the contribution of NK cells in tumor suppression of P29mtSAMP1 cybrids, we performed in vitro cytotoxic assays by co-cultivation of 51Cr-incorporated cybrids with activated NK cells prepared from the B6 Rag2-/- mice." (PMID 24098752, 2013). "A cell suspension sample from a tumor was re-injected into 3-4 Rag2-/- mice." (PMID 21269511, 2011). "In one series of experiments, we phenotyped each successive in vivo passage, and in one of the earlier passages, we noted the presence of some T cell receptor positive cells (which by definition must be of tumor origin since the Rag2-/- mice cannot rearrange the T cell receptor)." (PMID 21269511, 2011). "The tumor cells were subjected to several passages in vivo until we were able to generate stable tumor cell lines that could grow in Rag2-/- mice and in culture." (PMID 21269511, 2011). "However, the use of Rag2-knockout mice demonstrated that the adaptive immune response was required for tumour rejection." (PMID 18253127, 2008). "For example, the rag2 mutant line has been shown to be a useful model for human cancer xenotransplantation, while zebrafish prkdc mutants show 50–70% engraftment when injected intraperitoneally with tumor cells from human melanoma, leukemia, pancreatic cancer and bile duct cancer cell lines." (PMID 37047441, 2023).
tumor (continued). "Indeed, when Taves, Otsuka, and authors implanted B16 into Rag2-deficient mice, which lack T and B cells, the influence of 11β-HSD1 on tumor growth was no longer visible, indicating that GCs act in a paracrine manner on lymphocytes to promote tumor growth." (PMID 37712416, 2023). "Using mouse models for tumor transplantation and primary development, it was shown that non-immune-edited (immunogenic) sarcomas grown in rag2-deficient mice (which lack lymphocytes) were rejected by wild-type syngeneic mice; however IFNAR1 blockade abrogated this effect." (PMID 34925363, 2021). "Indeed, low-dose TSA delivery failed to inhibit tumor growth in the RAG2-deficient recipient mice, indicating that adaptive immune cells are required for the anti-tumor responses elicited by low-dose TSA treatment." (PMID 33564072, 2021). "In addition, we previously established a lymph node metastasis model of a subcutaneous tumour using recombination activating gene 2 (RAG2)-knockout (KO) immunodeficient swine to evaluate the cancer-bearing circumstance that closely reflects the clinical situation." (PMID 33705492, 2021). "Finally, to exhaustively rule out the reliance on an adaptive immune response for QBKPN efficacy, we tested whether QBKPN administration reduced tumor burden in RAG2 knockout mice which were sourced from colonies that tested positive for Klebsiella exposure." (PMID 29399400, 2018). "Additionally, we sought to determine the importance of adaptive immunity in regulating tumor growth and immune responses between these tumors using recombinase-activating gene 2 deficient (RAG2 KO) mice, lacking all B and T lymphocytes, including NKT cells." (PMID 21695190, 2011). "In line with the tumor responses, Kaplan-Meier analysis showed that indisulam treatment led to durable complete responses in both C57BL/6 and Rag2-/- mice." (PMID 40962798, 2025). "The increase in thymus size of diseased STAT5BN642HRag2–/– mice was the most drastic difference compared with Rag2–/–, WT, or STAT5BN642H mice, suggesting the development of immature T cell neoplasia." (PMID 38618957, 2024). "To investigate the effects of ASNS deletion in tumor progression, we used a cell-line derived cancer xenograft Rag2/IL2RG (R2G2) mouse model and performed a tumorigenicity study to examine tumor growth in vivo." (PMID 38886847, 2024). "Wild-type and RAG2-deficient mice displayed comparable initial tumour burdens; however, after 14 days, immunocompetent mice demonstrated local rejection of around 30% of individual tumours from the same array, while immunodeficient mice did not reject the tumours." (PMID 37258670, 2023). "The ability to xenograft tumor cell lines and PDX tissue in the RAG2/IL2RG knockout pigs orthotopically, provides a highly unique model for histotripsy development." (PMID 34478363, 2022). "Further genotyping of this animal revealed only a partial disruption of the RAG2 and IL2RG genes, resulting in an attenuated but still viable immune system that drove tumor rejection." (PMID 34478363, 2022). "To determine if STING-mediated tumor clearance is dependent on an adaptive immune response, we tested DMXAA treatment in Rag2 Knockout (KO) mice." (PMID 36700206, 2022). "To further investigate the immunogenicity of this model in its native tumor microenvironment, we transplanted B-ALL tumor cells into Rag-2 KO recipient mice, which lack functional T and B cells." (PMID 34711820, 2021). "To determine the potential contribution of T lymphocytes in inhibiting tumor growth, we analyzed the efficacy of low-dose TSA in tumor-bearing recombination activating gene 2 (RAG2) knock out (KO) mice." (PMID 33564072, 2021). "After overnight incubation, 2 C/Rag2–/– T cells were removed and the remaining resistant B16.SIY tumor cells were allowed to recover for 1 week." (PMID 32001684, 2020).
tumor (continued). "The evidence that fibroblasts are effective in promoting tumor initiation and progression in different mouse models of carcinogenesis prompted us to analyze whether co-injection of fibroblasts with C91/PL cells in newborn Rag2-/-γc-/- mice could facilitate the engraftments of this cell line." (PMID 29951044, 2018). "The third construct was rag2-GFP to track the tumors by fluorescence as they arose, as it has been shown that 100% of rag2-GFP-positive foci go on to eventually form a tumor." (PMID 23705022, 2013). "In our study, we implanted primary tumor pieces from 78 untreated patients (ranging from GS6-GS9) into the male NOD/SCID, Rag2, or NSG mice supplemented with testosterone at 3 different sites (i.e., SC, KC and/or AP)." (PMID 23451107, 2013). "Interestingly, in RAG2 KO mice deficient in all adaptive lymphocytes, including NKT cells, TM40D-MB tumor growth rates were significantly increased as compared to wildtype (P = 0.0127 at day 42 post tumor implantation), and similar to the rate of TM40D in wildtype." (PMID 21695190, 2011). "In this study, we used immunodeficient (i.e., Rag2-/-) transgenic GFAP-luc mice to grow orthotopic brain tumors and to monitor the co-activation of the GFAP promoter with tumor development." (PMID 21247490, 2011). "Only when both cDC1s and cross-dressed inflammatory monocytes were absent (B2m KO tumours engrafted into Rag2–/–Batf3–/– mice) did T cells fail to become restimulated." (PMID 39604727, 2025). "Moreover, similar to NTT tumours, YUMM1.7OVA RTT tumours with Ptgs2 KO or IRF3/7 overexpression were controlled in Rag2–/–Batf3–/– mice, which lack cDC1s." (PMID 39604727, 2025). "Notably, when NTT cells were injected into Rag2–/–Batf3–/– mice, which lack functional cDC1s, and ACT was performed, T cells still infiltrated, expanded and controlled NTT tumours." (PMID 39604727, 2025). "We established NTT tumours and RTT tumours of the YUMM1.7 mouse melanoma model (BrafV600E, Pten–/–Cdkn2a–/–) that express the model antigen ovalbumin (OVA) in Rag2–/– mice and performed ACT by intravenously injecting activated tumour antigen-specific CD8+ T cells (OT-1Luc)." (PMID 39604727, 2025). "We also found that the change in tumor cell composition of KP-HetHigh tumors at later timepoints observed in wildtype mice was also absent in Rag2-/- mutants." (PMID 37548358, 2023). "To assess the capability of TIINDRR to report tumor–immune interactions in diverse tissues, we adoptively transferred antigen-specific P14 CD8+ T cell receivers systemically into Rag2−/− mice with established YMR-mGFP metastases expressing the LCMV GP antigen (YMRGP)." (PMID 37871202, 2023). "Rag2 KO mice were injected subcutaneously with a low (0.5 × 106), medium (1 × 106), and high (2 × 106) number of the cetuximab-sensitive SC263-S and acquired cetuximab-resistant SC263-R cells and tumor growth was followed up over time." (PMID 38239393, 2023). "In Rag2-/- mice, neither PV-1 nor anti-PD-1 antibody treatment induced significant tumor inhibition." (PMID 38077406, 2023). "On Day 12, Rag2−/−‐OT1‐iT cells (1.0 × 107/mouse) which were derived from the spleens of Rag1−/− recipients transplanted with day21‐iHPCs for 6 weeks, were retro‐orbitally to these tumour‐bearing mice." (PMID 36592612, 2023). "SPATA2 and CYLD deficiency significantly reduced tumor growth in BALB/c mice but not in Rag2-/- BALB/c mice, suggesting that adaptive immune cells were required for tumor regression." (PMID 36531014, 2022). "STAT3 inhibition showed a minor, but not significant impact in tumor progression despite being implanted in Rag2/IL2rg-/- mice." (PMID 36443756, 2022). "The true appreciation of the immune response in suppressing tumor formation came when mice lacking adaptive immunity (RAG2 knock-out) showed an increased tumor incidence upon carcinogen exposure." (PMID 33807608, 2021). "SVs in ETV6-RUNX1 positive tumours bear the hallmarks for RAG1 and RAG2 activity." (PMID 34753926, 2021).
tumor (continued). "Due to the historic use of mice in IRE and other tumor ablation modality development, we next compared the Panc01 tumors grown in this study from the RAG2/IL2RG pigs with Pan02 tumors generated in immunocompetent mice and PDX tissue derived tumor generated in immunocompromised mice." (PMID 33828203, 2021). "CDA induced tumor regression even in Rag2-/- mice but was strongly depleted in Rag2-/- Il2rg-/- mice lacking NK cells, B, and T cells." (PMID 32823563, 2020). "To characterise the microenvironment of this tumour metastasis model, we analysed RAG2-knockout swine with and without metastatic tumours." (PMID 31138877, 2019). "To this end, we applied a similar tumor transplantation model using LLC and B16 tumor cells in RAG2 deficient animals, completely lacking mature T and B cells." (PMID 31214164, 2019). "Lymph nodes of wild-type and RAG2-knockout swine with or without A431-induced tumours were collected and subjected to histological analysis." (PMID 31138877, 2019). "RAG2 KO and MDR1A/RAG2 dKO mice were subjected to the AOM/DSS protocol and followed up to week 20, as initial results suggested delayed overall tumor development in both RAG2-deficient mice strains (data not shown)." (PMID 28686677, 2017). "RAG1 transcripts are not produced by human ALCL tumours (even though RAG2 transcripts are detectable in our murine NA/OTI tumours)." (PMID 26753883, 2016). "As expected, the CD4NA/RAG2−/− tumours, despite expressing CD4±CD8 do not display TCR rearrangements." (PMID 26753883, 2016). "On the other hand, T cell density distribution across the tumor in RAG2−/− mice fit a linear model, with a slope that did not significantly differ from a flat line (P>0.05, linear regression) (lower line)." (PMID 27177227, 2016). "BM cells from wild-type C57BL6 mice and the immune-deficient mouse strains B-cell−/−, CD28−/−, perforin−/−, and Rag2−/− but not CD11b−/− dramatically increased the expression of tumor cell surface PD-L1." (PMID 25889536, 2015). "Tumor-bearing recipients were SCID (lacking T, B, and NK cells), Rag2 deficient (lacking T and B cells), and wild-type BALB/c mice." (PMID 26090481, 2015). "In contrast, promotion of metastasis by nicotine is largely diminished in RAG2−/−β2−/− mice, as the tumor burden was indistinguishable between RAG2−/− and RAG2−/−β2−/− mice." (PMID 23469004, 2013). "N202.1A tumor growth kinetics was independent of Lov treatment when cells were implanted in immunodeficient RAG2−/− mice." (PMID 24317954, 2013). "In order to determine the extent to which human cells were able to inhibit K562 cell growth in vivo, tumor burden was measured in both reconstituted and non-reconstituted Rag2−/−/γc−/− mice." (PMID 20027308, 2009). "We found that indisulam treatment promoted a remarkable infiltration of NK cells in the c-MYC tumors implanted in Rag2-/- mice, and various immune cells, including T and NK cells in the transgenic TH-MYCN/ALKF1178L tumors, suggesting that indisulam induced an “inflamed” tumor microenvironment." (PMID 40962798, 2025). "To explore the in vivo anti-tumor activity of CAR/CCR T cells in comparison with CAR (2nd Gen) constructs, we intravenously injected 5 × 104 CD19+CD80highCD86high cells of the Burkitt B cell lymphoma cell line Raji on day −4 into Rag2– γc– immunocompromised mice." (PMID 38340727, 2024). "Moreover, genetic knockout Phf8 resulted in comparable tumor progression in immunodeficient Rag2-/- mice that do not have mature T and B cells." (PMID 37454216, 2023). "Consistent with nongenetic cellular heterogeneity in vitro, HARA cell tumors formed in the lungs of Rag2–/–Il2rg–/–Cd47–/– recipient mice were also heterogeneous with respect to calbindin protein, with clusters of positive and negative cells in the same tumor nodule." (PMID 37192000, 2023).
tumor (continued). "In addition to cell line tumors, we have also successfully generated PDX-like tissue and tissue organoids from humans and engrafted these more complex and physiologically relevant specimens into the RAG2/IL2RG knockout animals, opening the opportunity to move beyond cell line-based tumor models." (PMID 34478363, 2022). "Importantly, we also found that the number of total ILC2 cells were significantly increased in Rag2-/- PD-1-/- mice, further suggesting ILC2s play an important anti-tumor role independent of surrounding B and T cells." (PMID 34531874, 2021). "Finally, to assess if cis- versus trans costimulation could manifest in vivo in a tumor setting, HCT116-derived tumors were xenografted under the skin of immunodeficient Rag2−/− IL2Rγc−/− mice." (PMID 34911975, 2021). "Preliminary experiments conducted to xenograft, either i.p. or subcutaneously, the HTLV-1-immortalized C91/PL cell line at different doses (from 2 to 10 × 106 cells per mouse) in immunodeficient adult Rag2-/-γc-/- mice did not lead to tumor development (data not shown)." (PMID 29951044, 2018). "To study the effects of Endo II on HER2+ tumor growth and metastasis in vivo, we performed both mammary orthotopic xenograft assays and experimental metastasis assays in mice lacking natural killer (NK) cells, B cells and T cells (Rag2-/-:IL2Rγc-/-)." (PMID 28974266, 2017). "When LINC-PINT overexpressing HCT116 and A549 cells were injected subcutaneously into two different types of immunocompromised mice (nude and BALB/c-Rag2/‐IL2cc), they presented a decreased ability to form tumors, indicating that LINC-PINT inhibits the aggressiveness of the tumor cells." (PMID 29078818, 2017). "On the other hand, in the absence of T cells (i.e. in RAG2−/− tumor recipients), the host has no T cells that may infiltrate the tumor." (PMID 27177227, 2016). "Culture-activated L-selectinlow TDLNs from BALB/c wild-type mice were able to cure Rag2 deficient but not SCID mice bearing 4T1 subcutaneous tumors, suggesting a requirement of NK cells within the innate immune system of the tumor-bearing host during the antitumor response." (PMID 26090481, 2015). "Luciferase-expressing MDA-MB-231 cells stably expressing non-targeting control shRNA (“control cells”) or shRNA1 (“shRNA cells”) were orthotopically implanted into the inguinal mammary fat pads of female Rag2−/− Il2rg−/− mice and tumor growth was monitored by non-invasive bioluminescent imaging." (PMID 26452220, 2015). "Therefore to test expression localization, we compared our Ad5ROBO4 versus Ad5CMV vectors in a nine organ panel harvested from tumor bearing immunodeficient Rag2−/− mice (negative littermate mice derived from hCAR:Rag2−/− × Rag2−/− matings)." (PMID 24376772, 2013). "In addition, as RAG2−/− mice have no intrinsic T and B cells, the role for nAChR β2 in determining the effect of nicotine in tumor metastasis is likely via NK cells." (PMID 23469004, 2013). "For xenograft studies, we implanted tumor pieces (∼2–3 mm3) at three different anatomical sites, i.e., subcutis (s.c), kidney capsule (KC), or anterior prostate (AP) in one of the three immunodeficient mouse strains, i.e., NOD/SCID, Rag2−/−, or NOD/SCID-IL2Rγ−/− (NSG) mice." (PMID 23451107, 2013). "Unfortunately, neither experimental group exhibited any sustainable tumor growth, indicating that these cell lines were also unsuitable as progressive HNSCC models in the Rag2 KO mouse strain." (PMID 38239393, 2023). "Spontaneous HEVs did not occur in B16-OVA tumors grown in Rag2-/- mice, lacking B and T lymphocytes but appeared when Rag2-/- mice were reconstituted with CD8 T cells before tumor implantation." (PMID 34484246, 2021). "To directly address the effects of Myc B on HER2+ cancer metastasis independent of effects on tumor growth, we performed tail vein injections of SKOV3-Luc cells mixed with either Saline/DMSO control or Saline/Myc B in female Rag2−/−:IL2γc−/− mice." (PMID 30467396, 2018).